CD28 (CD28 molecule)
Description:
Receptor that plays a role in T-cell activation, proliferation, survival and the maintenance of immune homeostasis. Functions not only as an amplifier of TCR signals but delivers unique signals that control intracellular biochemical events that alter the gene expression program of T-cells. Stimulation upon engagement of its cognate ligands CD80 or CD86 increases proliferation and expression of various cytokines in particular IL2 production in both CD4(+) and CD8(+) T-cell subsets. Mechanistically, ligation induces recruitment of protein kinase C-theta/PRKCQ and GRB2 leading to NF-kappa-B activation via both PI3K/Akt-dependent and -independent pathways. In conjunction with TCR/CD3 ligation and CD40L costimulation, enhances the production of IL4 and IL10 in T-cells. [Isoform 3]: Enhances CD40L-mediated activation of NF-kappa-B and kinases MAPK8 and PAK2 in T-cells.
Synonyms: IMD123; Tp44
Tractability: Small molecule: a structure with a bound ligand is known. Antibody: a drug acting on it is in phase 2 or 3 trials; UniProt places it where antibodies can reach, with high confidence; its Gene Ontology location is reachable by antibodies, with high confidence; UniProt predicts a signal peptide or a membrane-spanning region; the Human Protein Atlas places it where antibodies can reach. PROTAC: ubiquitination databases record sites on it.
Gene: Protein-coding gene on chromosome 2 (203,706,517 to 203,739,756, forward strand). Ensembl gene ENSG00000178562.
Subcellular location: Cell membrane; Cell surface (Isoform 3)
Subcellular location (Human Protein Atlas): Plasma membrane
Pathways (Reactome):
Immune System: CD28 dependent PI3K/Akt signaling; CD28 dependent Vav1 pathway; Co-stimulation by CD28
Disease: Constitutive Signaling by Aberrant PI3K in Cancer; Nef mediated downregulation of CD28 cell surface expression
Signal Transduction: PI5P, PP2A and IER3 Regulate PI3K/AKT Signaling; PIP3 activates AKT signaling
Gene Ontology:
Molecular function: protein binding; transmembrane signaling receptor activity; coreceptor activity; identical protein binding; protein kinase binding
Biological process: negative regulation of gene expression; positive regulation of gene expression; positive regulation of interleukin-10 production; positive regulation of interleukin-2 production; positive regulation of interleukin-4 production; positive regulation of mitotic nuclear division; positive regulation of T cell proliferation; positive regulation of T cell receptor signaling pathway; regulatory T cell differentiation; T cell activation; cell surface receptor signaling pathway; humoral immune response; negative regulation of apoptotic process; positive regulation of cytokine production; positive regulation of translation; positive regulation of viral genome replication; T cell costimulation; T cell receptor signaling pathway; immune response; immune system process; positive regulation of T cell activation; regulation of T cell proliferation
Cellular component: cell surface; external side of plasma membrane; plasma membrane; protein complex involved in cell adhesion; cytosol; immunological synapse; membrane
Genetic constraint (gnomAD): Loss-of-function variants: 6 observed, 18.69 expected, observed/expected ratio (o/e) 0.32, 90% interval 0.17 to 0.63. The upper end of that interval is the gene's LOEUF score, 0.63, which puts it in group 2 of 6, group 1 being the genes least tolerant of losing a copy. Missense variants: 224 observed, 265.35 expected, observed/expected ratio (o/e) 0.84, 90% interval 0.76 to 0.94. Synonymous variants: 103 observed, 103.96 expected, observed/expected ratio (o/e) 0.99, 90% interval 0.84 to 1.17.
Gene-disease validity (ClinGen):
ClinGen rates the evidence that CD28 causes each of these diseases.
immunodeficiency 123 with HPV-related verrucosis (autosomal recessive): Moderate.
Homologues: Orthologues: chimpanzee CD28 (100% identical), macaque CD28 (98% identical), rabbit CD28 (78% identical), pig CD28 (77% identical), dog CD28 (74% identical), guinea pig CD28 (72% identical), mouse Cd28 (68% identical), tropical clawed frog cd28 (22% identical), zebrafish si:dkey-1h24.6 (20% identical). Paralogues in human: CTLA4 (27% identical).
Diseases named in the same sentence as CD28 in open-access papers:
CD28 is named in the same sentence as 442 diseases in open-access papers, as found by Europe PMC text mining. Sharing a sentence is not in itself a finding about the gene and the disease. The quoted sentences say what the papers report.
autoimmune disease (110 papers, 2006 to 2026). A disorder resulting from loss of function or tissue destruction of an organ or multiple organs, arising from humoral or cellular immune responses of the individual to their own tissue constituents. "The functional integrity of the CD28 molecule was necessary for CTLA-4 knockout mice to cause autoimmune diseases, implying that CTLA-4 suppresses the autoimmunity caused by the CD28 signaling pathway." (PMID 37497212, 2023). "Our research investigated multiple autoimmune disease-related SNPs in checkpoint molecules and found that CD28 rs1980422 is a risk factor for ITP susceptibility, which provides new evidence of the impact of immune checkpoints on ITP." (PMID 33584705, 2020). "Costimulatory signals are required for both tTreg and pTreg cell generation; indeed, mice deficient in CD28 signaling harbor reduced numbers of both Treg types, leading to autoimmune diseases." (PMID 29510522, 2018). "In particular, it would be of high interest to analyze the presence of CD4+CD28− T cells, which have been implicated in both autoimmune diseases like rheumatoid arthritis, MS and Graves’ disease, but also specifically in relation to CMV infection." (PMID 26956521, 2016). "By contrast, the hyper-reaction of the B7/CD28 signal is closely associated with the occurrence of autoimmune diseases." (PMID 26096149, 2015). "SNPs in the CD28/CTLA4/ICOS gene region were reported to be associated with several autoimmune diseases including, type-1 diabetes, systemic lupus erythematosus, autoimmune thyroid diseases and celiac disease." (PMID 22911710, 2012). "Polymorphisms in the CD28 gene were previously shown to be genetically associated with autoimmune diseases, such as rheumatoid arthritis and Bechet’s disease." (PMID 23133541, 2012). "Hyperreactivity of B7/CD28 signaling is closely linked with the development of autoimmune diseases." (PMID 38524638, 2024). "CD4+ CD28- T cells are associated with autoimmune diseases like rheumatic arthritis." (PMID 39399489, 2024). "Therefore, CD28 can either reduce or enhance the susceptibility to autoimmune diseases by altering T-cell effector and Treg cell compartments." (PMID 29904580, 2018). "Likewise, Foxp3-cre-mediated deletion of CD28 in autoimmune disease models causes loss of suppressive activity by Treg cells." (PMID 29510522, 2018). "Interestingly, genome-wide studies on patients have associated single nucleotide polymorphisms in the CD28 gene to increased risk for autoimmune disease." (PMID 29163534, 2017). "Indeed, this specific CD28 deficiency in Treg resulted autoimmune disease was prevented by supplementation with wild type CD28 expressing Treg20." (PMID 28223693, 2017). "Of note, the lack of CD28 expression is also a hallmark of senescent T cells, which are known to be increased in various autoimmune diseases and chronic inflammatory conditions and may show a rather aggressive phenotype." (PMID 16859514, 2006). "This balance between the CTLA-4, CD28, and B7 proteins ensures that T cells can fight infections and cancer while preventing excessive or harmful immune responses, such as autoimmune diseases." (PMID 41155258, 2025). "Manipulating CD28 co-stimulation is a key element of anti-tumour immune responses and treating autoimmune diseases." (PMID 40496752, 2025). "CD28 is a regulator of glucose metabolism and a key player in various immune-related diseases, such as asthma, autoimmune diseases like lupus, and Graves’ disease." (PMID 40806007, 2025). "It indicates that blocking the CD80/CD28 costimulatory signaling pathway with 4E5 is a very promising strategy to slow the progression of lupus-like diseases and other autoimmune diseases." (PMID 39575257, 2024). "Physiological aging, viral infection and autoimmune disease can induce the downregulation of CD28 expression on CD8+ T cells." (PMID 36721233, 2023).
autoimmune disease (continued). "CD4+ CD28- T cells are a subset of cytotoxic cells that are increased in autoimmune diseases and with persistent infections such as HIV." (PMID 36865544, 2023). "The coordination of CTLA-4 and CD28 maintains the balance of T-cell immunity in the body, especially after infection and the onset and progression of autoimmune disease." (PMID 37497212, 2023). "Selective CD28 antagonists are currently being tried in the treatment of autoimmune diseases, confirming their role in suppressing overactivated autoimmunity." (PMID 36969245, 2023). "The soluble form of CTLA-4, capable of binding CD80, is implicated in the pathogenesis of several autoimmune diseases, in which sCTLA-4 is able to inhibit early T-cell activation by blocking the interaction between CD80 and the costimulatory receptor CD28." (PMID 37483633, 2023). "After mice were given CD28 antagonists, it was found that CD28 antagonists were able to induce antigen-specific tolerance and prevent autoimmune diseases and organs." (PMID 36246590, 2022). "Metabolic reprogramming occurs generally downstream of TCR and the co-stimulatory receptor (such as CD28) signaling following interaction between T cells and APCs in autoimmune disease, which activates mTORC1 and MYC signaling." (PMID 35401560, 2022). "It is known that CD28 acts as an essential role in bacterial pneumonia, lethal shock, and pulmonary fibrosis in autoimmune diseases." (PMID 35184642, 2022). "An imbalance in the expression or hyperstimulation of CD28 has been realized either in the form of transplantation failures or in the development of autoimmune diseases." (PMID 35076538, 2022). "Given the considerable interest in inducing suppressive T cells as a therapeutic strategy for autoimmune diseases and organ transplantation, our finding also unveils the CD28 costimulatory pathway as a potential target." (PMID 34011962, 2021). "Previous studies have shown that the CD28:B7 pathway plays a critically important role in the pathogenesis of many autoimmune disease including psoriasis." (PMID 34354596, 2021). "An inappropriate balance of CTLA4 and CD28 can result in T‐cell overactivation by CD28 and autoimmune disease." (PMID 33598480, 2021). "We acknowledge that our NPs did not include components of antigen specificity, differently from the paramagnetic iron-dextran NPs that expressed peptide/MHC and anti-CD28 antibodies and were used in organ-specific autoimmune diseases." (PMID 34122401, 2021). "We have previously shown that both anti-CD28 and soluble TNFα inhibited the expression of PTPN22, a gene that is associated with several autoimmune diseases, but only anti-CD28 promoted the production of IL-17A/F in anti-CD3 stimulated PBMCs." (PMID 34301319, 2021). "FR104 is a monovalent humanized Fab’ antibody fragment antagonist of CD28 that was pegylated to prolong its half-life, under development for the treatment of transplant rejection and autoimmune diseases." (PMID 34354596, 2021). "CD8+ T cells that lack surface expression of CD28 (CD8+CD28− Treg) have been widely documented in autoimmune diseases and inflammatory conditions." (PMID 34831195, 2021). "Abatacept, a CTLA-4–Ig fusion protein that blocks the CD28-mediated costimulatory signal necessary for T-cell activation, has been tested in phase I clinical trials for several autoimmune diseases." (PMID 34298735, 2021). "For example, in mice with Treg-selective deletion of CD28, Ubc13, Helios or Ezh2, impaired Treg in vivo suppressive activity is accompanied by development of spontaneous autoimmune diseases, yet in vitro Treg inhibitory function remained normal." (PMID 33024109, 2020). "A gene locus in chromosome 2q33, which contains CTLA4 and CD28, is associated with the risk of T1DM, autoimmune thyroiditis and other autoimmune diseases." (PMID 33272321, 2020).
autoimmune disease (continued). "Due to the relevance of IL-17A in the pathophysiology of several inflammatory and autoimmune diseases, we characterized the mechanisms and signaling mediators responsible for CD28-induced IL-17A expression." (PMID 31068940, 2019). "Although co-stimulation by CD28 on T cells is essential for modulating the T-cell immune response in autoimmune diseases, inhibitory pathways by CTLA-4 on T cells are also critical." (PMID 31747403, 2019). "While competition with CD28 can occur, the induction of autoimmune disease in Ctla-4−/− mice depends on a C-terminal intracellular proline CD28 motif in in vivo co-stimulation." (PMID 30542345, 2018). "Manyin vivo mouse models have been used for understanding the role of CD28 in the maintenance of immune homeostasis, thus leading to the development of CD28 signaling modulators that have been approved for the treatment of some autoimmune diseases." (PMID 29904580, 2018). "The importance of CD28 in vivo has been demonstrated through the use of anti-CD28 therapies to induce immunosuppression following transplantation, in patients with autoimmune diseases and during cancer immunotherapies via CD28 activation." (PMID 29329537, 2018). "Here, we discuss CD28 regulatory functions in mouse models of autoimmune diseases by showing the success and failure of pre-clinical studies when translated to humans." (PMID 29904580, 2018). "In a knockout CD28 mouse model of autoimmune disease with a reduced absolute number of Tregs, the authors observed an increase in autoimmunity response in the animals, suggesting that CD28 is involved in Treg expansion and consequently their function." (PMID 29693595, 2018). "Although B7/CD28 co-stimulation participates in the induction and progression of autoimmune diseases, it has also been demonstrated that B7/CD28 co-stimulatory molecules interaction is substantial for Tregs development and proliferation." (PMID 29416823, 2018). "In the case of CTLA-4, studies have shown that autoimmune disease in Ctla4−/− (i.e. CTLA-4) mice depend on CD28 expression." (PMID 31544130, 2017). "Altogether, these features encouraged researchers to consider CD28 blockade as a promising tool for immunomodulation in autoimmune diseases." (PMID 28248972, 2017). "The inhibition of the CD28-dependent T cell activation has been used as a therapeutic tool for several autoimmune diseases." (PMID 29123529, 2017). "The blockade of the CD28 pathway with CTLA-Ig in animal models of autoimmune diseases prevented the progression of the disease [reviewed in Ref." (PMID 29123529, 2017). "Quantitative changes of a CD8+CD28− (CD8+CD57+) lymphocytes population have been observed in autoimmune diseases such as multiple sclerosis, type 1 diabetes, Graves' disease, and rheumatoid arthritis." (PMID 27446964, 2016). "In our study, the percentages of annexin V-positive apoptotic cells were indistinguishable between WT and Hrd1 cKO T cells on in vitro TCR/CD28 stimulation or in mice during autoimmune disease development." (PMID 27417417, 2016). "CD4+CD25+FoxP3+ regulatory T (Treg) cells and CD8+CD28- Treg cells have roles in autoimmune diseases." (PMID 27211045, 2016). "This is especially important for the treatment of autoimmunity, where the initial priming event would have already occurred, and explains how CD28 intervention is effective at controlling ongoing autoimmune disease." (PMID 25347065, 2014). "It provides further rationale for targeting B cells and costimulatory pathways, such as ICOS and CD28, in autoimmune diseases by highlighting their potential to dampen autoreactive responses by eliminating both GC B cells and Tfh cells." (PMID 25101629, 2014). "CD28/B7 co-stimulation is involved in the induction and progression of autoimmune diseases, but its role in controlling murine Th17 cell fate remains to be clarified." (PMID 19333372, 2009). "These unexpected results caution targeting the CD28/B7 pathways in the treatment of human autoimmune diseases." (PMID 19333372, 2009).